MAPKAPK5 (MAPK activated protein kinase 5)
Description:
Tumor suppressor serine/threonine-protein kinase involved in mTORC1 signaling and post-transcriptional regulation. Involved in post-transcriptional regulation of MYC by mediating phosphorylation of FOXO3: phosphorylation of FOXO3 leads to promote nuclear localization of FOXO3, enabling expression of miR-34b and miR-34c, 2 post-transcriptional regulators of MYC that bind to the 3'UTR of MYC transcript and prevent MYC translation. Acts as a negative regulator of mTORC1 signaling by mediating phosphorylation and inhibition of RHEB. Part of the atypical MAPK signaling via its interaction with ERK3/MAPK6 or ERK4/MAPK4: the precise role of the complex formed with ERK3/MAPK6 or ERK4/MAPK4 is still unclear, but the complex follows a complex set of phosphorylation events: upon interaction with atypical MAPK (ERK3/MAPK6 or ERK4/MAPK4), ERK3/MAPK6 (or ERK4/MAPK4) is phosphorylated and then mediates phosphorylation and activation of MAPKAPK5, which in turn phosphorylates ERK3/MAPK6 (or ERK4/MAPK4). Mediates phosphorylation of HSP27/HSPB1 in response to PKA/PRKACA stimulation, inducing F-actin rearrangement.
Synonyms: MAPKAP-K5; MK-5; MK5; PRAK; NCFD
Tractability: Small molecule: a drug acting on it is in phase 2 or 3 trials; a high-quality ligand is known; it belongs to a druggable protein family. PROTAC: it is named in the literature on targeted protein degradation; ubiquitination databases record sites on it; a small molecule that binds it is known.
Target class: CAMK protein kinase group; Kinase; Enzyme; CAMK protein kinase MAPKAPK subfamily; Protein Kinase; CAMK protein kinase MAPKAPK family
Gene: Protein-coding gene on chromosome 12 (111,842,013 to 111,902,222, forward strand). Ensembl gene ENSG00000089022.
Subcellular location: Cytoplasm; Nucleus
Subcellular location (Human Protein Atlas): Nucleoplasm; Cytosol
Pathways (Reactome):
Cellular responses to stimuli: Oxidative Stress Induced Senescence
Signal Transduction: MAPK6/MAPK4 signaling
Gene Ontology:
Molecular function: protein binding; protein serine/threonine kinase activity; MAP kinase kinase activity; mitogen-activated protein kinase binding; ATP binding; protein kinase activity; protein serine kinase activity
Biological process: positive regulation of telomere maintenance; positive regulation of transcription by RNA polymerase II; protein autophosphorylation; Ras protein signal transduction; regulation of translation; stress-induced premature senescence; cellular senescence; negative regulation of TOR signaling; signal transduction; MAPK cascade; regulation of intracellular signal transduction
Cellular component: cytosol; nucleoplasm; cytoplasm; nucleus; protein-containing complex; septin cytoskeleton
Genetic constraint (gnomAD): Loss-of-function variants: 19 observed, 46.19 expected, observed/expected ratio (o/e) 0.41, 90% interval 0.29 to 0.6. The upper end of that interval is the gene's LOEUF score, 0.6, which puts it in group 2 of 6, group 1 being the genes least tolerant of losing a copy. Missense variants: 365 observed, 475.78 expected, observed/expected ratio (o/e) 0.77, 90% interval 0.7 to 0.84. Synonymous variants: 157 observed, 168.15 expected, observed/expected ratio (o/e) 0.93, 90% interval 0.82 to 1.07.
Homologues: Orthologues: macaque MAPKAPK5 (99% identical), dog MAPKAPK5 (99% identical), pig MAPKAPK5 (98% identical), mouse Mapkapk5 (97% identical), guinea pig MAPKAPK5 (97% identical), chimpanzee MAPKAPK5 (94% identical), rabbit MAPKAPK5 (93% identical), tropical clawed frog mapkapk5 (91% identical), zebrafish mapkapk5 (87% identical), Drosophila melanogaster MAPk-Ak2 (31% identical). Paralogues in human: MAPKAPK2 (33% identical), MAPKAPK3 (32% identical), CAMK4 (26% identical), MKNK2 (25% identical), MKNK1 (24% identical), DCX (10% identical).
Diseases named in the same sentence as MAPKAPK5 in open-access papers:
MAPKAPK5 is named in the same sentence as 64 diseases in open-access papers, as found by Europe PMC text mining. Sharing a sentence is not in itself a finding about the gene and the disease. The quoted sentences say what the papers report.
Obesity (5 papers, 2015 to 2023). Accumulation of substantial excess body fat. "Other genes in MAPK signaling that are not significant according to the gene scores (RPS6KA4, DUSP4, MAPKAPK5) have also been associated with obesity." (PMID 37860106, 2023). "miR-148a might modulate fat deposition by targeting MAPKAPK5, MAPK3, and MAP2K2, and miR-148 has been shown to affect obesity and modulates adipocyte differentiation." (PMID 28293627, 2017).
prostate carcinoma (5 papers, 2012 to 2025). A carcinoma that arises from epithelial cells of the prostate gland. "And TMEM116, HECTD4, MAPKAPK5 was reported to be associated with renal cell carcinoma, prostate cancer and colorectal cancer." (PMID 35096568, 2021). "Our screen also identified other stress kinases, including MAP3K7, MAP4K3, and MAPKAPK5 (data not shown), which underscores the critical nature of stress kinase signaling in regulating prostate cancer cell growth." (PMID 22761715, 2012).
Anxiety (2 papers, 2007 to 2014). Intense feelings of nervousness, tension, or panic often arise in response to interpersonal stresses. "Our results revealed anxiety-related traits and locomotor differences between transgenic mice expressing constitutive active MAPKAPK5 and control littermates." (PMID 17997833, 2007). "Since little remains known about the MAPK-Activated Protein Kinase, MAPKAPK5, we constructed the first MAPKAPK knockin mouse model, using a constitutive active variant of MAPKAPK5 and analyzed the resulting mice for changes in anxiety-related behaviour." (PMID 17997833, 2007).
cognitive decline (2 papers, 2015 to 2022). "The use of longitudinal change in CANTAB-PAL, a cognitive test that is sensitive to early cognitive decline, was critical in the discovery of MAPKAPK5 as a potential biomarker relevant to AD." (PMID 26080319, 2015). "MAPKAPK5 correlated with cognitive decline in the Twins UK cohort; however, its relationship with neuropathology is unknown." (PMID 35475137, 2022).
Coffin-Siris syndrome (1 paper, 2023). Coffin-Siris syndrome (CSS) is a rare congenital multi-systemic genetic disorder characterized by aplasia or hypoplasia of the distal phalanx or nail of the fifth digit, developmental delay, intellectual disability, coarse facial features, and other variable clinical manifestations. "There is also some overlap between the phenotype of MAPKAPK5-related NDD and Coffin-Siris syndrome, but the nail dysplasia in the former does not typically affect the nails of the fifth fingers or little toes." (PMID 36581449, 2023).
gastric cancer (1 paper, 2022). A primary or metastatic malignant neoplasm involving the stomach. "We found that MAPKAPK5 and USP1 proteins were highly expressed in gastric cancer tissues, while the ZFP36 protein was lowly expressed in tumor tissues." (PMID 35719376, 2022).
gout (1 paper, 2022). A condition characterized by painful swelling of the joints, which is caused by deposition of urate crystals. "The involved genes were ABCG2, SLC2A9, PKD2, ZNF518B, ALDH2, HECTD4, and MAPKAPK5 in the phenotype of gout; and only gene SLC2A9 was found in the AH phenotype." (PMID 36221101, 2022). "The results revealed that the variants exhibited protective effects against developing gout, namely rs3733589 (SLC2A9), rs3775948 (SLC2A9), rs1014290 (SLC2A9), rs3109823 (ABCG2), rs2622604 (ABCG2), rs6532055 (ABCG2), rs72554040 (ABCG2), rs671 (ALDH2), rs78069066 (MAPKAPK5), and rs77768175 (HECTD4)." (PMID 36221101, 2022).
Hypoglycemia (1 paper, 2021). A decreased concentration of glucose in the blood. "In control subjects, HSPB1, SMAD3 and HSPA1A decreased significantly, whilst MAPKAPK5 increased significantly in controls from baseline to hypoglycemia whilst, in T2D, PPP3CA increased and EPHA2 decreased." (PMID 34426634, 2021).
mesothelioma (1 paper, 2021). A usually malignant and aggressive neoplasm of the mesothelium which is often associated with exposure to asbestos. "MK5, also known as MAPKAPK5, has recently been shown to be a positive regulator of YAP in both mesothelioma and uveal melanoma, by its association with YAP preventing CK1δ/ε-mediated proteasomal degradation." (PMID 33557087, 2021).
neurocardiofaciodigital syndrome (1 paper, 2023). "Recently, homozygous loss-of-function variants in MAPKAPK5 were reported in four patients from three families presenting with a recognisable neurodevelopmental disorder, so-called ‘neurocardiofaciodigital’ syndrome." (PMID 36581449, 2023).
pancreatic NET (1 paper, 2016). "We found a novel p.I16fs MAPKAPK5 mutation involved in the MAPK signaling pathway in a patient with pancreatic NET." (PMID 26684240, 2016).
tumor (27 papers, 2007 to 2025). "The present study found that MAPKAPK5 was negatively related to increased risk score, providing further evidence that MAPKAPK5 acts as a tumor suppressor." (PMID 35721059, 2022). "MAPKAPK5 encodes a protein that belongs to the serine/threonine kinese family and plays a role as a tumour suppressor." (PMID 34576052, 2021). "MAPKAPK5 upregulation is associated with high expression of the transcriptional regulator YAP and poor prognosis in clinical tumor samples, and its positive regulation of YAP activity plays an important role in human cancers." (PMID 36497289, 2022). "MAPKAPK5 is known to be involved in tumor suppression, angiogenesis, and cytoskeletal remodeling through interaction with a variety of substrates and is associated with neurological processes, including neurosecretion." (PMID 26684240, 2016). "MAPKAPK5 is therefore a tumor inhibitor that disrupts the negative feedback loop with myc during CRC tumorigenesis." (PMID 35721059, 2022). "More specifically, miR-34c is thought to act as a tumor suppressor as part of a negative feedback loop including Myc and Mapkapk5, part of the MAPK signalling pathway." (PMID 22974136, 2012).
cancer (13 papers, 2012 to 2025). A tumor composed of atypical neoplastic, often pleomorphic cells that invade other tissues. "On the other hand, binding of MK5 (also called MAPKAPK5 or PRAK) to Yap stabilizes Yap independent of Lats1/2, which is required for Yap-driven cancer progression." (PMID 33869224, 2021).
infection (2 papers, 2012 to 2023). The state of being infected such as from the introduction of a foreign agent such as serum, vaccine, antigenic substance or organism. "In NHBE and THP-1 cells, five mitogen-activated protein kinase (MAPK) family members (MAP2K3, MAP2K6, MAPKAPK2, MAPKAPK3, MAPKAPK5) showed decreased activity or no significant change during pH1N1 infection, and increased activity during H3N2 and H5N1 infection." (PMID 37758692, 2023).
MAPKAPK5 also shares sentences with these, for which no sentence is quoted: colorectal cancer (4 papers); renal fibrosis (4); skin tumor (4); Alzheimer disease (3); bacterial infection (3); lung carcinoma (3); breast carcinoma (2); cardiac hypertrophy (2); diabetes (2); ischemic stroke (2); melanoma (2); metabolic disorders (2); myocardial infarction (2); myocardial ischemia (2); Sepsis (2); skin cancer (2); skin papilloma (2); Stroke (2); brain injury (1); cardiovascular disease (1); Cerebral ischemia (1); chlamydial infection (1); colon cancer (1); colorectal tumor (1); fatty liver disease (1); fibrosis (1); glomerulonephritis (1); Glucose intolerance (1); Hypercholesterolemia (1); Hyperglycemia (1).
A further 20 diseases each share a sentence with MAPKAPK5 in 1 paper.